STAT1 (signal transducer and activator of transcription 1)
Diseases named in the same sentence as STAT1 in open-access papers (continued):
Sharing a sentence is not in itself a finding about the gene and the disease.
tumor (continued). "The transcription factor Stat1 is essential for innate immunity and tumor immunosurveillance through its ability to act downstream of interferons." (PMID 18941537, 2008). "Tumour cells can naturally develop mutations on IFN-γ downstream target genes, such as JAK and Stat1, to render them insensitive to IFN-γ." (PMID 17622250, 2007). "In a recent study, activated STAT1 was also shown to negatively regulate angiogenesis, tumorigenicity and metastasis of tumour cells." (PMID 12865928, 2003). "Moreover, fludarabine targeting STAT1 in combination with anti-PD-1 has a synergetic effect on suppressing tumor growth in mice." (PMID 41623183, 2026). "Internalized TNFAIP8 recruits the E3 ligase TRIM21 to facilitate STAT1 ubiquitination and degradation, leading to the induction of myofibroblastic CAF-associated features, accompanied by enhanced extracellular matrix deposition and tumor growth." (PMID 41709860, 2026). "Immunofluorescent analysis of primary tumor tissues further revealed a dose-dependent increase in phosphorylated STAT1 within M2 TAMs (pSTAT1+/CD206+) following rWISP-1 treatment in a dose-dependent manner, whereas no significant change was observed in M1 TAMs (pSTAT1+/CD86+)." (PMID 41522359, 2026). "In xenograft models, the impaired tumor growth induced by IGF2BP2 inhibition could be reinstated by si-STAT1." (PMID 41522349, 2026). "In early-stage MF, we observed gene expression differences in cells of both the stroma and the immune system, with keratinocytes exhibiting increased interferon response and proliferation (STAT1, ICAM1, HLA-DRA, GJB2), while fibroblasts displayed tumour-associated programs (CXCL2, TNFAIP6, CEBPD)." (PMID 41888970, 2026). "Furthermore, the RNA level of CCL5 is significantly correlated with Stat1 in tumor tissues of the TCGA_ESCA dataset, with a correlation coefficient reaching 0.575." (PMID 40995650, 2025). "The mechanisms by which STAT1 inhibits tumor development may be related to both cytokine-dependent and -independent effects." (PMID 40287766, 2025). "To test this hypothesis, we aim to elucidate differences in expression profiles of the two protein-coding STAT1 isoforms (α and β) across healthy and tumor tissues." (PMID 40849492, 2025). "Moreover, suppression of SLC14A1+ CAF development through STAT1 or STING inhibition enhances tumor cell vulnerability to chemotherapeutic agents." (PMID 41301792, 2025). "It remains unclear whether the IFN-γ/STAT1 signaling regulates the immune escape for tumor progression demonstrated here by CXCL10/CXCR3." (PMID 40909948, 2025). "Through the p50 NF-κB signaling pathway, tumor-derived PGE2 facilitates the binding of STAT1 to the regulatory regions of IFNγ-dependent genes, such as inducible nitric oxide synthase (Nos2), thereby promoting NO production and contributing to immune suppression." (PMID 40612857, 2025). "Importantly, STAT1 activation as well as MHCII was significantly increased in tumor tissue, validating our prior data." (PMID 41429766, 2025). "Both 3′ UTR SNPs may interfere with STAT1 regulation by creating new miRNA binding sites that downregulate its expression, potentially impairing its tumor suppressor effect." (PMID 40407590, 2025). "The pivotal gene STAT1 was confirmed to demonstrate its essential function in tumor immunogenicity." (PMID 40226609, 2025). "TPST2 modulates the tumor immune microenvironment via tyrosine sulfation of interferon gamma receptor 1 (IFNGR1) at residue Y397, attenuating STAT1 signaling, reducing HLA expression and antigen presentation, and consequently diminishing tumor-infiltrating lymphocytes." (PMID 41403951, 2025). "Trajectory analysis revealed that C2_STAT1+ cells were derived from the C1_EGFR+ cell population, marking a transcriptional shift of tumor cells toward a highly immunosuppressive and multidrug-resistant tumor phenotype." (PMID 40948762, 2025). "DCs present tumor cell antigens to CD4+ T cells through the Jak/STAT1 signaling pathway." (PMID 40612857, 2025).
tumor (continued). "Interestingly, in addition to regulating the immune response, activation of STAT1 increased the apoptosis of cancer cell and suppressed tumor cell proliferation." (PMID 40786029, 2025). "Lactate activation of HCAR1 indeed suppressed STAT1/2 transcriptional activity and downregulated the expression of target genes, which might represent an intrinsic mechanism promoting tumor progression." (PMID 40956299, 2025). "A dysfunctional STAT1 variant, which is unable to translocate into the nucleus upon cytokine stimulation and fails to inhibit STAT3, can trigger lymphomagenesis, as STAT3 becomes more active and contributes to lymphoid malignancy and tumor progression." (PMID 40287766, 2025). "As KRAS has been shown to suppress STAT1 transcription, we hypothesize that PTDSS1 loss impairs RAS signaling, which in turn releases the suppression of STAT1 expression, enhancing tumor cell responsiveness to IFN-γ in a cell-intrinsic manner." (PMID 40929270, 2025). "Furthermore, the proliferation of tumor cells was significantly reduced when STAT1 was either knocked down or inhibited, suggesting that the abnormal activation of STAT1 is a crucial factor in the pathogenesis of ETV6-NTRK3-positive tumors." (PMID 40584293, 2025). "Most data indicate that STAT1 activation has a tumor suppressor function in cancer cells." (PMID 40407590, 2025). "The expression of p-STAT1 was found to be lower in HCC tumor tissues than in adjacent normal liver tissues, consistent with the observation that the suppression of STAT1 activity was correlated with HCC progression and prognosis in a set of HCC patient samples." (PMID 39826687, 2025). "Tumor growth was suppressed upon VitC treatment, and this effect could be again correlated with vitcylation of STAT1 in tumor cells, using similar strategies as in the in vitro experiments." (PMID 40583064, 2025). "Concurrently, IFNγ can upregulate Acyl-CoA Synthetase Long Chain Family Member 4 expression through STAT1/IRF1 signaling, facilitating the integration of tumor microenvironment-associated arachidonic acid into phospholipids, inducing ferroptosis in tumor cells." (PMID 40136510, 2025). "Activation of STAT1 is generally associated with antitumor immune responses that promote antigen presentation and cytotoxic T cell recruitment, while activation of STAT3 often promotes tumor cell survival, angiogenesis and immunosuppression." (PMID 40760734, 2025). "Similarly, the RNA level of Stat1 is elevated in pre‐therapy tumor tissues from responders compared with non‐responders in the PRJEB23709 database." (PMID 40995650, 2025). "Similarly, syndecan-1 (SDC1) restrained IFN-γ-STAT1 signaling and antigen presentation in tumor cells and thereby attenuated the sensitivity to T cell-mediated cytotoxicity and induced immunotherapy resistance." (PMID 40524231, 2025). "However, STING-dependent activation of NF-κB RelB-IL-6-STAT3 was shown to promote tumor cell proliferation by blocking STAT1-induced apoptosis." (PMID 40691137, 2025). "CDK8 was also reported to regulates the activation of STAT1 and NK cell cytocytoxity in tumor." (PMID 40888963, 2025). "Moreover, in isolated tumor cells, the N-terminally truncated STAT1 and, to a much lesser extent STAT3, were hyperphosphorylated irrespective of cytokine stimulation, as compared to non-transformed spleen cells from their WT-expressing littermates." (PMID 40287766, 2025). "In this study, we show that therapeutic stress induces a previously unrecognized STAT1 modification that weakens tumor immune response, linking prior targeted therapy to immunotherapy resistance and highlighting implications for treatment scheduling and patient stratification." (PMID 41205596, 2025). "Therefore, elucidating the molecular mechanisms underpinning the inhibitory effects of the IFN-γ/STAT1 pathway on tumor progression is of paramount significance for advancing therapeutic strategies in oncology." (PMID 40909948, 2025).
tumor (continued). "IFNG is upstream of STAT1 and activates its anti-tumor effects by binding to IFNGR1." (PMID 40659662, 2025). "The role of the activated STAT1 as either a tumor suppressor or a tumor promoter has been reported." (PMID 39900908, 2025). "Combined with photothermal therapy, CD@MSNs can stimulate NK cells to secrete IFN-γ, which might activate STAT1, promote the polarization of TAMs towards the M1 phenotype, and achieve immune-mediated suppression of tumor metastasis." (PMID 40302816, 2025). "USP5 depletion facilitates the transfer of tumor-intrinsic p-STAT1/2 to macrophages." (PMID 41321309, 2025). "We hypothesize that following the concurrent activation of STAT1 by the two drugs, STAT1 functions as a transcription factor to further regulate the expression of related genes, thereby suppressing tumor growth." (PMID 40659662, 2025). "Finally, STAT1 has been described as both a tumour suppressor and an oncogene in different contexts." (PMID 40956832, 2025). "In addition to the downregulation of STAT1 signal transduction, tumor cells showed reduced NF-κB (p65) expression and a slight decrease in the LPS-induced degradation of IκBα." (PMID 40287766, 2025). "The SPHK1-S1P signalling axis has also been reported promote the survival of breast CSCs through blocking the tumour suppressor function of signal transducer and activator of transcription 1 (STAT1), with SPHK1 inhibitors sensitising these cells to cell death induced by doxorubicin." (PMID 41253780, 2025). "For example, STAT1 is involved in the expression of immune checkpoint PD-L1 expression on neutrophils and attraction of immunosuppressive neutrophils populations to the tumor site." (PMID 40050933, 2025). "Previous studies have demonstrated that the upregulation of p21 expression, mediated by IFN-γ through the activation of STAT1, effectively suppresses tumor cell proliferation, as shown in cell line A431 (oral epidermoid carcinoma) and cell lines HT29 and WiDr (colon adenocarcinoma)." (PMID 40909948, 2025). "Some authors have suggested that the function of STAT1 as an oncogene or tumor suppressor may be dependent on menopausal status." (PMID 41463071, 2025). "We concluded that, in the comparison between cytokine-stimulated NHL cells expressing mutant STAT1 and WT-expressing control cells, there was a decrease in STAT1-mediated gene expression in the tumor cells, whereas genes upregulated by STAT3 were induced at higher rates." (PMID 40287766, 2025). "Importantly, STAT1 acetylation in pre-treatment tumor samples predicts ICB efficacy, underscoring its potential as a clinically relevant biomarker for guiding immunotherapy decisions." (PMID 41205596, 2025). "Here, AF1q may support tumor suppression, possibly through the involvement of the pro‐apoptotic STAT1 axis." (PMID 40062505, 2025). "Moreover, STING has been shown to enhance tumor cell survival through the activation of the IFN/STAT1 signaling pathway, underscoring its complex and dual role in tumor immunity." (PMID 41200171, 2025). "Furthermore, it is revealed that this process strengthens the interferon signaling pathway by stabilizing STAT1 phosphorylation, thereby activating the anti-tumor immune response." (PMID 40346580, 2025). "The STAT1 agonist SB02024 was administered intraperitoneally when tumor volumes reached 100 mm3." (PMID 40346580, 2025). "Mechanistic investigations revealed that CXCL7 activates the CXCR2 receptor on tumor cells, triggering interferon signaling and promoting serine metabolism through STAT1-dependent transcriptional upregulation of phosphoglycerate dehydrogenase (PHGDH), the key enzyme in serine biosynthesis." (PMID 40368902, 2025). "Previous studies also reported that IFI44L, TRIM22, OAS1, OAS2, and MX2 inhibited tumor proliferation and metastasis, indicating that the transcriptional regulation of STAT1/2 could limit the development of OS." (PMID 40956299, 2025).
tumor (continued). "Finally, our findings were further validated by demonstrating that LINC00543 regulated the tumour immune microenvironment in CRC by downregulating STAT1/STAT2 expression." (PMID 39868645, 2025). "Indeed, in our model, STAT1 upregulation following arginine deprivation appears to reflect a stress-induced adaptive state that enhances tumor resilience." (PMID 41511309, 2025). "Additionally, upregulation of antigen presentation genes including H2-Aa, H2-Ab1, H2-Eb1, Tapbp and Cd74 as well as Stat1 and Cxcl9 - a chemokine that recruits immune cells to the tumor, was observed in the CAR-T group." (PMID 40568084, 2025). "STAT1 phosphorylation of neutrophils in B16-F10 tumor tissues was blocked in mice treated with Flu." (PMID 40226609, 2025). "This activation inhibits STAT1-mediated transcription, impairing tumor cell-intrinsic immunity." (PMID 40739089, 2025). "Importantly, the induction of Stat1 knockdown in murine OSCC cells led to sustained tumor growth despite anti-PD1 administration, whereas significant tumor shrinkage was observed in the control group." (PMID 41205596, 2025). "Interestingly, protein arginine methyltransferase 1 (PRMT1) is identified as a negative regulator of MHC‐I expression, attenuating CD8+ T cell‐mediated anti‐tumour responses by suppressing IFN‐γ‐induced STAT1 activation." (PMID 40673641, 2025). "Analysis of metastatic CRC samples mirrored these findings: STAT1-high tumors exhibited more immunogenic microenvironments, characterized by higher tumor and stromal MHC-I/PD-L1 expression and increased TILs, along with transcriptomic signatures of IFNγ, HLA-A/E/G, and cytotoxic effectors." (PMID 41293269, 2025). "Many downregulated genes in tumour‐infiltrating peripheral CD8+ T cells are associated with classical IFN responses (IFI6, IFI27, MX1, STAT1, EPSTI1 PARP9, ISG15), cell proliferation (STMN1, CENPF, HELLS, NUSAP1, and DNPH1), and T cell costimulation (CD28, TMIGD2, TNFRSF4, CD27, and TNFRSF18)." (PMID 39350478, 2024). "Subsequently, our candidate HPV DNA vaccine CRT/E7 was administered to determine whether the STAT1−/− host preserves a therapeutic-responsive tumor microenvironment." (PMID 38675812, 2024). "In other cell types, AXL has been shown to block STAT1-dependent responses, thus it is tempting to speculate it may similarly function to block the STAT1 tumor suppressor in CSCs, enhancing CIN tolerance." (PMID 39345336, 2024). "Therefore, the downregulation of miR-21 increases STAT1 and macrophage M1 polarization, increasing phagocytosis and anti-tumor immunity." (PMID 38339019, 2024). "In TI-Tregs, the feedback loop of STAT1-IFITM3 was associated with Treg function, and the perturbation of this loop may affect anti-tumor immunity." (PMID 38167862, 2024). "In this study, we confirmed that ROS induces STAT1 degradation in tumor cells, suggesting that STAT1 degradation during CAC progression might be induced by ROS." (PMID 39575303, 2024). "Moreover, their responses to the tumor microenvironment differ, exemplified by STAT1 and GREM1 upregulation in HOSE1C and HOSE2C, respectively." (PMID 39634630, 2024). "Therefore, the tumor control in STAT1−/− mice can be attributed to the E7-specific CD8+ T-cell population." (PMID 38675812, 2024). "Our findings demonstrate that spontaneous tumor growth was more rapid when using STAT1−/− mice." (PMID 38675812, 2024). "In addition, the tumor suppressors STAT1 and human leukocyte antigen class I (HLA-A) were downregulated." (PMID 39474419, 2024). "The utilization of PD-L1 blockers elicits the secretion of IFN-γ by CD8+T cells, leading to the inhibition of transcription and expression of SLC7A11 and SLC3A2, thereby reducing GPX4 production via the JAK1/STAT1 pathway and facilitating ferroptosis in tumor cells." (PMID 38853203, 2024).
tumor (continued). "Type I IFN signaling helped maintain stable STAT1 levels and activate tumor regulatory T cells." (PMID 38672681, 2024). "In addition, we further challenged the control and STAT1−/− mice with direct tumor cell implantation to elucidate their retention of a responsive host immune system." (PMID 38675812, 2024). "However, there is still debate on the role of STAT1 in immuno-oncology, either as a tumor promoter or suppressor, depending on the specific cancer type." (PMID 38675812, 2024). "Upon CRT-E7 administration, STAT1−/− mice responded to the vaccine by demonstrating tumor control." (PMID 38675812, 2024). "Notably, IHC analysis of 50 clinical HCC tumor samples showed that HKDC1 expression levels were positively correlated with STAT1 phosphorylation and PD-L1 protein levels." (PMID 38351096, 2024). "First, STAT1−/− mice had greater tumor growth than control mice." (PMID 38675812, 2024). "Our ongoing studies aim to see whether restoration of NLRC5 and/or use of dsRNA analog such as poly I:C can actually enhance antigen presentation, T cell-mediated tumor cell killing, and sensitivity to ICB in HNSCC models with deficient IFN/STAT1 signaling." (PMID 38231444, 2024). "Mechanically, PTA reinforces the anti-tumor ability of Th9 cells primarily through upregulating interleukin (IL)-1β and subsequently activating the downstream STAT1/IRF1 pathway, which could be effectively blocked by intercepting IL-1β signaling." (PMID 38760861, 2024). "Previous studies have revealed that STAT1 has both carcinogenic and tumor suppressive functions in different cancers, which may depend on the background of the cancer cells." (PMID 38764020, 2024). "The STAT1 performs the following functions, acting as an anti-infection, inhibiting cell proliferation, regulating the immune system, enabling cell differentiation, inhibiting tumor growth, inhibiting cell growth, and promoting cell apoptosis." (PMID 39539545, 2024). "Finally, we report a reciprocal inhibition between TP63 and STAT1 at the transcription level, which determines anti-tumor immune response of SCC cells by regulating the IFNγ signaling." (PMID 38509096, 2024). "STAT1 functions as a tumor suppressor in various malignancies." (PMID 39575303, 2024). "Combining anti-PD-L1 antibodies with ferroptosis inducers has shown significant efficacy in inhibiting tumor growth, attributed to the release of interferon-γ by cytotoxic T cells, which activates STAT1 and inhibits xCT expression, thereby promoting ferroptosis." (PMID 39015566, 2024). "Research has revealed that the STAT1/RIG-I axis plays a significant part in anti-tumor processes." (PMID 39055888, 2024). "Specifically, YTHDF2, by interacting with RBM4, facilitates the degradation of m6A-modified mRNAs of Signal Transducer and Activator of Transcription 1 (STAT1), thereby inhibiting the polarization of M1 TAMs, consequently diminishing both the innate and adaptive anti-tumor immunity of TAMs." (PMID 39342406, 2024). "However, activated STAT1 expression in the tumor microenvironment is positively correlated with the upregulation of PD-L1, thus suppressing intratumoral T-cell activities." (PMID 38675812, 2024). "We found that IL12, IL27, and IFNγ, which could increase the STAT1 expression to induce Th1 response in the tumor microenvironment, could also induce high expression of IFITM3 of Treg cells." (PMID 38167862, 2024). "In addition, we also determined that known downstream signaling molecules activated by interferon-gamma receptors associated with macrophages, namely STAT1, IRF1, and IRF5, were also correlated with poor OS outcomes in tumor samples." (PMID 38539537, 2024). "In addition, vaccinated STAT1−/− mice demonstrated significantly less total luciferase intensity than unvaccinated STAT1−/− mice, suggesting a better controlled tumor response in vaccinated STAT1−/− mice." (PMID 38675812, 2024).